DUSP6 (dual specificity phosphatase 6)
Diseases named in the same sentence as DUSP6 in open-access papers (continued):
Sharing a sentence is not in itself a finding about the gene and the disease.
endometrial cancer (8 papers, 2013 to 2025). Primary or metastatic malignant neoplasm involving the endometrium (mucous membrane that lines the endometrial cavity). "As DUSP6 expression was also positively associated with worse progression‐free and overall survival, DUSP6 represents a potential biomarker for endometrial CSCs and a therapeutic target in endometrial cancers." (PMID 32159851, 2020). "Along this line, another study performed in endometrial cancer cells, showed that DUSP6 overexpression in the Ishikawa cell line led to a decrease in ERK1/2 phosphorylation and E-cadherin expression." (PMID 40943262, 2025). "But DUSP6 plays a tumor suppressor in endometrial cancer, low DUSP6 levels activating the ERK pathway to promote tumor progression." (PMID 40936711, 2025). "In our study, we focused on DUSP6 functions in endometrial cancers and demonstrated that DUSP6 plays various roles related to CSC phenotype." (PMID 32159851, 2020). "To determine the clinical relevance of DUSP6, we investigated DUSP6 protein expression in 90 archived human endometrial cancer specimens using IHC." (PMID 32159851, 2020). "Collectively, these results suggest that DUSP6 expression in endometrial cancer cells induces CSC characteristics." (PMID 32159851, 2020). "In patients with endometrial cancers, DUSP6 expression was determined using immunohistochemistry, and based on the results, the patients were dichotomized into high‐ and low‐DUSP6‐expression groups." (PMID 32159851, 2020). "The DUSP6 promoter was demonstrated to be target for PEA3 family proteins in two previous ChIP-seq studies in ECC-1 endometrial carcinoma cells and PC3 prostate cancer cells." (PMID 28859074, 2017). "However, gene alterations in PTRD as well as in SKAP1 and DUSP6 regions require further experimental studies to validate their actual contribution to the development of endometriosis and endometrial cancer." (PMID 35563789, 2022). "We investigated whether DUSP6 is involved in cancer cell stemness using endometrial cancer cell lines and specimens from endometrial cancer patients." (PMID 32159851, 2020). "We also assessed the requirement for DUSP6 in endometrial cancer metastasis in vivo." (PMID 32159851, 2020). "In our study, we demonstrated that DUSP6 supports a CSC phenotype in endometrial cancer cells." (PMID 32159851, 2020). "However, hypermethylation of the DUSP6 promoter, which may determine a reduction of DUSP6 expression, has been reported to be a rare event in endometrial cancer." (PMID 40943262, 2025). "We found that DUSP6 was associated with short progression‐free survival (PFS) and overall survival (OS) in patients with endometrial cancer and thus may be a therapeutic target in the CSCs of patients with endometrial cancer." (PMID 32159851, 2020). "In addition, in patients with endometrial cancers, DUSP6 expression may be related to short PFS and OS." (PMID 32159851, 2020). "DUSP6 may stimulate the expression of CSC‐related genes in endometrial cancer cells." (PMID 32159851, 2020). "Furthermore, methylation of DUSP6 is infrequent in endometrial cancer." (PMID 24260056, 2013). "Other potential candidates for gene alterations correlated with both endometriosis and endometrial cancer are located nearby the SKAP1 and DUSP6 genes." (PMID 35563789, 2022). "DUSP6 was also positively related to apoptosis inhibition, starvation resistance, invasion, metastasis and short PFS and OS in patients with endometrial cancers." (PMID 32159851, 2020). "In conclusion, DUSP6 contributed to a CSC phenotype by increasing self‐renewal ability and starvation resistance, and its expression was required for maintaining the invasive and metastatic abilities of endometrial cancer cells." (PMID 32159851, 2020). "Despite this study providing evidence that DUSP6 may counteract endometrial cancer progression, it has not been reported whether DUSP6 expression is reduced or increased in this type of tumour." (PMID 40943262, 2025).
endometrial cancer (continued). "Therefore, silencing of DUSP6 may not be involved in the constitutive activation of the ERK kinase cascade in endometrial cancer." (PMID 24260056, 2013). "Dual‐specificity phosphatase 6 (DUSP6) functions as a negative‐feedback regulator of MAPK–ERK1/2 signaling, but its role in endometrial cancer remains unknown." (PMID 32159851, 2020).
hepatocellular carcinoma (8 papers, 2012 to 2025). A malignant tumor that arises from hepatocytes. "On the other hand, hsa‐miR‐200a‐3p increases 5‐FU resistance by downregulating Dual Specificity Phosphatase 6 (DUSP6) in hepatocellular carcinoma." (PMID 40444136, 2025). "In human hepatocellular carcinoma, miR-200a-3p targets dual-specificity phosphatase 6 (DUSP6) to augment cancer cell resistance to 5-fluorouracil, doxorubicin, and cisplatin." (PMID 36158660, 2022). "miR-200a-3p was shown to target dual-specificity phosphatase 6 (DUSP6) and enhance the sensitivity of hepatocellular carcinoma cells to 5-fluorouracil (5-FU)." (PMID 35682560, 2022). "Interestingly DUSP6-mediated negative regulation of p38 has been demonstrated in hepatocellular carcinoma, where enhanced polyubiquitination and the degradation of DUSP6 contributed to the increased phosphorylation of p38." (PMID 34943871, 2021). "The combination of 3-HAA and sorafenib was demonstrated to sensitize hepatocellular carcinoma (HCC) cells by upregulation of phosphatases PPP1R15A/DUSP6 which reduced AKT phosphorylation and activity." (PMID 36232383, 2022).
bipolar disorder (7 papers, 2013 to 2022). A disorder of the brain that causes unusual shifts in mood, energy, activity levels and the ability to carry out day-to-day tasks. "ERK1/2, a selective target for DUSP6, has been implicated as one of the important regulators mediating the pathogenesis and therapeutic mechanisms of bipolar disorder." (PMID 35630630, 2022). "Another study detected an association between DUSP6 and bipolar disorder and highlighted the impact of DUSP6 on the therapeutic effects of lithium." (PMID 33384710, 2020). "The appearance of some DUSP6 SNPs or genetic variants constitutes risk factors, among others, in some psychiatric diseases, such as bipolar disorder (BD)." (PMID 31018603, 2019). "The DUSP6 gene is located on chromosome region 12q22-q23 identified as bipolar disorder susceptibility loci." (PMID 31018603, 2019). "Among these were BDNF, VGF, WFS1, DUSP6, CRHBP, MAOA, and RELN, which have previously been implicated in bipolar disorder." (PMID 31114610, 2019). "One of the key genes in this pathway, DUSP6, a cytoplasmic phosphatase that plays an active role in MAPK signaling by regulating the intensity and duration of MAPK activity and by helping to shuttle MAPK between the cytoplasm and nucleus, has been associated with bipolar disorder." (PMID 23358228, 2013). "DUSP6 and DUSP1 gains of function behave as markers of the progression and prognosis of bipolar disorder and depressive behavior, respectively, and they are responsible for deficient ERK signaling in these pathologies." (PMID 31018603, 2019).
leukemia (7 papers, 2012 to 2024). A malignant (clonal) hematologic disorder, involving hematopoietic stem cells and characterized by the presence of primitive or atypical myeloid or lymphoid cells in the bone marrow and the blood. "Indeed, several mRNAs associated with the development of leukaemia, including Dusp6, Klf4, and Plxnb2, were significantly elevated in ECs and resting leukaemia cells after chemotherapy." (PMID 38674015, 2024). "While both control and DUSP6-overexpressing BB-z CAR-T cells controlled leukemia progression, only control CAR-T cells induced progressive weight loss in treated mice." (PMID 29765028, 2018). "In contrast, the mice infused with the DUSP6-CAR-T cells survived without leukemia relapse or weight loss." (PMID 29765028, 2018). "Despite the known role of DUSP6 as negative regulator of ERK1/2 activation, which was also observed in FLT3 ITD-expressing leukemia cells, DUSP6 was identified as a positive component in the FLT3 ITD-driven proliferation." (PMID 22784513, 2012). "Importantly, DUSP6-CAR-T cells showed similar persistence compared with control CAR-T cells in mice rechallenged with NALM6-GL and prevented leukemia progression." (PMID 29765028, 2018).
neuroblastoma (7 papers, 2005 to 2025). Neuroblastoma (NB) is the most common solid, extracranial childhood tumor. "Significantly, we found that both nuclear DUSP1 and cytosolic DUSP6 phosphatases were expressed strongly in serum deprived N2a neuroblastoma cells." (PMID 36589747, 2022). "Recently, studies performed with the DUSP1/DUSP6 inhibitor BCI showed that p38 activation also upregulates P2X7R levels in neuroblastoma cells, indicating that the DUSP1 phosphatase may negatively modulate P2X7R expression by dampening the p38 pathway." (PMID 37776398, 2024). "MKPs, and particularly DUSP1 and DUSP6, have been proposed as cancer biomarkers, since aberrant expression of these phosphatases has been found in a wide variety of human cancers, including neuroblastoma." (PMID 36589747, 2022). "Retinoid treatment of MYCN transgenic mice bearing neuroblastoma altered the expression of five of nine target genes examined (RARβ2, CYP26A1, CRBP1, DUSP6, PLAT) in neuroblastoma tumour tissue in vivo." (PMID 16012519, 2005). "This study examined whether the cytotoxic effects of BCI on neuroblastoma tumour cells were exerted by its known inhibitory action on dual specificity phosphatases DUSP1 and DUSP6." (PMID 35478300, 2022). "Combined, rather than individual, inhibition of DUSP6 and RGS16 was required to block retinoid-induced growth inhibition in neuroblastoma cells, through phosphorylation of extracellular-signal-regulated kinase." (PMID 16012519, 2005). "Enhance P2X7 receptor expression by downregulation of the p38 pathway in neuroblastoma cells, and exert cytotoxicity after deletion of DUSP6 and DUSP1 (CRISPR-Cas9) in neuroblastoma cells, suggesting that BCI cytotoxicity does not depend on DUSP1 or DUSP6 status in neuroblastoma cells." (PMID 41158869, 2025).
colorectal cancer (6 papers, 2021 to 2024). A primary or metastatic malignant neoplasm that affects the colon or rectum. "High expression of MDM2/CY and DUSP6/SN was significantly associated with a higher risk of colorectal cancer with OR ranges of 5.95–10.62 and 2.14–3.82, respectively." (PMID 36672653, 2023). "In colorectal cancer, miR‐452‐5p promoted tumor progression by targeting PKN2 and DUSP6 to activate the ERK/MAPK signaling pathway." (PMID 37014625, 2023). "The presence of the CPEB4/DUSP6 combination is a prerequisite for the significance of MMD, which supports the reported five-gene model for colorectal cancer." (PMID 36672653, 2023). "Overall, DUSP6, MDM2, and EIF2S3 were consistently selected as significant factors associated with colorectal cancer in all logistic models and were not modulated by any other genes or clusters." (PMID 36672653, 2023). "TRIM65 accelerates colorectal cancer metastasis by targeted degradation of ARHGAP35 protein, promotes the invasion of endometrial stromal cells through DUSP6 ubiquitination, activates ERK1/2/C-myc signals, and promotes bladder cancer cells through ubiquitination and degradation of ANXA2 invasion." (PMID 36035221, 2022). "TRIM65 has also been shown to promote colorectal cancer metastasis through targeted ubiquitination and degradation of ARHGAP35 protein and activates ERK1/2/C-myc signaling by targeting ubiquitination to degrade DUSP6 protein, thereby promoting the invasion of endometrial stromal cells." (PMID 36035221, 2022).
glioma (6 papers, 2015 to 2025). A benign or malignant brain and spinal cord tumor that arises from glial cells (astrocytes, oligodendrocytes, ependymal cells). "The IHC findings confirmed the increased expression of AEBP1, DCTD, DEPP1, DUSP6, FKBP9, and UGCG with the up‐regulation of glioma grades." (PMID 40052358, 2025). "Significant upregulation of Dusp6 and Fli1 gene expressions and downregulation of Hmox1 and Jun gene expressions in BV2 microglia, 2 h post segregated coculture with C6 glioma cells, were confirmed by RT-qPCR analysis." (PMID 39019900, 2024).
myocardial infarction (6 papers, 2017 to 2026). Gross necrosis of the myocardium, as a result of interruption of the blood supply to the area, as in coronary thrombosis. "Deletion of Dusp6 in mice improves cardiac outcomes by reducing neutrophil-mediated myocardial damage induced by myocardial infarction-caused inflammation." (PMID 37098604, 2023). "While we did not observe difference in numbers of neutrophils between DUSP6 KO and WT, neutrophils function can be enhanced by DUSP6, and KO mice were reported to have attenuated acute inflammation after myocardial infarction." (PMID 38974475, 2024). "Furthermore, a DUSP6 inhibitor has been tested in myocardial infarction rats, showing that it improves heart function and suppresses inflammatory cardiac remodeling." (PMID 37098604, 2023).
colon cancer (5 papers, 2018 to 2022). "The suppressive effect of FGF7 on ISG expression and the concomitant increase in DUSP6 expression was also observed with the Caco‐2 colon cancer cell line, which is responsive to FGF7." (PMID 32720440, 2020). "There was a significantly positive relation between PKN2 and DUSP6 expression in human colon cancer tissues." (PMID 29368606, 2018). "The phosphatase activity assays showed that PKN2 increased the activity of DUSP6 in colon cancer cell lines." (PMID 29368606, 2018). "Co-immunoprecipitation(Co-IP) assay showed that DUSP6 directly interacted with PKN2 in colon cancer cell lines." (PMID 29368606, 2018). "DUSP6 expression in human colon cancer tissues was evaluated by IHC." (PMID 29368606, 2018).
esophageal squamous cell carcinoma (5 papers, 2012 to 2025). Esophageal squamous cell carcinoma (ESCC) is a type of esophageal carcinoma (EC) that can affect any part of the esophagus, but is usually located in the upper or middle third. "In this study, 64.2% (61/95) of esophageal squamous cell carcinoma (ESCC) specimens studied exhibited reduced DUSP6 protein expression, compared with 91% (81/89) of normal esophageal specimens that displayed moderate or strong DUSP6 protein expression in tissue microarray analysis." (PMID 24260056, 2013). "Moreover, DUSP6 downregulation has led to the progression and differentiation of esophageal squamous cell carcinoma (ESCC)." (PMID 31950060, 2019). "Recently, DUSP6 was shown to inhibit growth, migration and epithelial-to-mesenchymal transition (EMT) of esophagal squamous cell carcinoma and nasopharyngeal carcinoma cells." (PMID 22784513, 2012).
sarcoma (5 papers, 2022 to 2026). A usually aggressive malignant neoplasm of the soft tissue or bone. "Finally, a study conducted on sarcoma cells (NCC_CDS_X1) revealed that the oncoprotein CIC-DUX binds to DUSP6, causing a decrease in ERK1/2 phosphorylation and consequent overexpression of the oncoprotein." (PMID 40943262, 2025). "Among the DUSPs inhibitors that have demonstrated a good antitumour efficacy, BCI, a benzoil-derivative small-molecule inhibitor of DUSP1 and DUSP6, has been reported to reduce BC, MPNST, LUAD, GC and sarcoma growth." (PMID 40943262, 2025). "The use of DUSP6 inhibitors is not in clinical use largely due to the potential negative effects of activating ERK in non-CIC::DUX4 sarcoma." (PMID 38882060, 2024). "Moreover, they identify that CIC::DUX4 transcriptionally upregulates DUSP6 to silence ERK activity and sustain CIC::DUX4 oncoprotein expression in sarcoma." (PMID 38882060, 2024). "In CIC-DUX4 sarcomas, the negative feedback loop of ERK/CIC/DUSP6 turns into a positive feedback axis, where the CIC-DUX4 fusion product leads to overexpression of DUSP6 and shut down of ERK signaling, promoting CIC-DUX4 retention in the nucleus and its target genes transcription." (PMID 36358827, 2022).
cardiac hypertrophy (4 papers, 2015 to 2024). "ERK1/2, the most important factor affecting cardiac hypertrophy, has been shown to be dephosphorylated and inactivated by DUSP6." (PMID 34858216, 2021). "Following long term pressure overload of 14 weeks after TAC the DUSP6 overexpressing mice did show more cardiac hypertrophy of the eccentric type with dilation, inflammation, and reduced function." (PMID 26257652, 2015). "Namely, the results indicated that in the heart tissue, DUSP6 promoted ERK1/2 dephosphorylation, thereby partially ameliorating diabetes-induced cardiac hypertrophy." (PMID 34858216, 2021). "However, complete inhibition of ERK1/2 mediated by DUSP6 overexpression did not reduce cardiac hypertrophy after pressure overload stimulation, neuroendocrine agonist infusion, or physiologic exercise stimulation." (PMID 27941647, 2016). "This study, which included overexpression of DUSP6, cannot support the hypothesis that cardiac hypertrophy could develop completely independent of ERK1/2, since DUSP6 may have other targets rather than ERK1/2." (PMID 27941647, 2016).
nasopharyngeal carcinoma (4 papers, 2012 to 2025). A carcinoma arising from the nasopharyngeal epithelium. "The role of DUSP6 in tumourigenesis has also been investigated in ESCC and nasopharyngeal carcinoma (NPC)." (PMID 40943262, 2025).
papillary thyroid carcinoma (4 papers, 2012 to 2019). "The overexpression of DUSP6/MKP-3 in papillary thyroid carcinoma (PTC) cell lines is also associated with increased cell migration and invasion." (PMID 30401534, 2019). "Moreover, DUSP6 has recently been found as a predictor of invasiveness in papillary thyroid cancer." (PMID 22784513, 2012).
prostate carcinoma (4 papers, 2010 to 2023). A carcinoma that arises from epithelial cells of the prostate gland. "FBXO31, the member of protein-ubiquitin ligase, activates ERK- and suppresses PI3K-AKT-mediated signaling pathways in prostate cancer by promoting the degradation of DUSP6." (PMID 36688696, 2023). "In prostate cancer, the degradation of DUSP6 played a key role in regulating the extension and duration of ERK activation, and promoted prostate tumorigenesis." (PMID 35458535, 2022). "Five other PS up-regulated genes (MERTK13, APLP2, CLDN 3, DUSP6 and TFPI) have been found to be overexpressed in prostate cancer and many other tumor types, but their role in tumor biology is less understood." (PMID 20500816, 2010).
acute lymphoblastic leukemia (3 papers, 2018 to 2021). Leukemia with an acute onset, characterized by the presence of lymphoblasts in the bone marrow and the peripheral blood. "Indeed, Markus Müschen's laboratory has previously shown that DUSP6 activity is essential to tame ERK1/2 activity in pre‐B acute lymphoblastic leukemia (ALL) cells." (PMID 33955157, 2021). "Finally, in acute lymphoblastic leukemia (ALL) DUSP6 acts as pro-oncogenic phosphatase in pre-B cell transformation." (PMID 32771050, 2020). "Ectopic expression of DUSP6 did not compromise cytokine secretion or the cytolytic activity of CAR-T cells against the CD19+ acute lymphoblastic leukemia cell line NALM6 in vitro." (PMID 29765028, 2018).
acute myeloid leukemia (3 papers, 2023 to 2025). Acute myeloid leukemia (AML) is a group of neoplasms arising from precursor cells committed to the myeloid cell-line differentiation. "Decreased DUSP6 correlates to increased migration in PDAC and ATF3 regulates DUSP6 expression in secondary acute myeloid leukemia through direct binding of the Dusp6 gene." (PMID 41198649, 2025). "Another study identified the increased expression of DUSP6 as a key factor in the progression of secondary acute myeloid leukaemia (sAML) by promoting JAK-STAT and ERK signalling, inflammatory cytokine production, and resistance to JAK2 inhibitors." (PMID 40943262, 2025).